KRT74 (keratin 74)
Description:
Has a role in hair formation. Specific component of keratin intermediate filaments in the inner root sheath (IRS) of the hair follicle (Probable).
Synonyms: K6IRS4; KRT5C; KRT6IRS4; ADWH; ECTD7; HTSS2; HYPT3
Tractability: PROTAC: ubiquitination databases record sites on it.
Gene: Protein-coding gene on chromosome 12 (52,565,782 to 52,573,843, reverse strand). Ensembl gene ENSG00000170484.
Subcellular location (Human Protein Atlas): Intermediate filaments; Cytosol; Nucleoli
Pathways (Reactome):
Developmental Biology: Formation of the cornified envelope; Keratinization
Gene Ontology:
Molecular function: keratin filament binding; protein binding; structural constituent of skin epidermis
Biological process: intermediate filament cytoskeleton organization; intermediate filament organization; keratinization
Cellular component: cytoplasm; extracellular exosome; cytosol; keratin filament
Genetic constraint (gnomAD): Loss-of-function variants: 39 observed, 39.87 expected, observed/expected ratio (o/e) 0.98, 90% interval 0.76 to 1.28. The upper end of that interval is the gene's LOEUF score, 1.28, which puts it in group 5 of 6, group 1 being the genes least tolerant of losing a copy. Missense variants: 711 observed, 683.32 expected, observed/expected ratio (o/e) 1.04, 90% interval 0.98 to 1.11. Synonymous variants: 294 observed, 276.09 expected, observed/expected ratio (o/e) 1.06, 90% interval 0.97 to 1.17.
Homologues: Orthologues: chimpanzee KRT74 (99% identical), macaque KRT74 (95% identical), pig KRT74 (84% identical), dog KRT74 (81% identical), guinea pig KRT74 (72% identical). Paralogues in human: KRT73 (74% identical), KRT71 (74% identical), KRT72 (71% identical), KRT3 (58% identical), KRT76 (58% identical), KRT4 (57% identical), KRT5 (57% identical), KRT6A (56% identical), KRT6B (56% identical), KRT6C (56% identical), KRT2 (56% identical), KRT1 (55% identical), and 56 more.
Diseases named in the same sentence as KRT74 in open-access papers:
KRT74 is named in the same sentence as 13 diseases in open-access papers, as found by Europe PMC text mining. Sharing a sentence is not in itself a finding about the gene and the disease. The quoted sentences say what the papers report.
hypotrichosis (4 papers, 2014 to 2025). A congenital condition, usually due to genetic aberrations, that is characterized by a lack of hair growth on the head and/or body. "Previous research has demonstrated that variants in KRT74 are associated with autosomal dominant wooly hair and hypotrichosis." (PMID 40766069, 2025).
hypotrichosis simplex (2 papers, 2014 to 2025). Hypotrichosis simplex (HS) or hereditary hypotrichosis simplex (HHS) is characterized by reduced pilosity over the scalp and body (with sparse, thin, and short hair) in the absence of other anomalies. "Moreover, relevant studies have discovered that mutations in the KRT71 and KRT74 genes might result in the symptoms of Hypotrichosis simplex (HS) and wooly hair (WH)." (PMID 40941372, 2025). "Heterozygous mutations in KRT74 have been shown to cause autosomal dominant woolly hair (MIM 194300), and/or hypotrichosis simplex (MIM 613981; collectively ADWH)." (PMID 24714551, 2014).
alopecia (1 paper, 2025). Hair loss usually from the scalp. "Given the strong association between alopecia and genetic variants, particularly in pediatric cases, whole exome sequencing (WES) was performed, revealing a heterozygous KRT74 variant (c.59C > A)." (PMID 40766069, 2025). "The absence of alopecia in the proband’s mother and brother, who share the same KRT74 variant, suggests potential incomplete penetrance or polygenic modulation of the phenotype." (PMID 40766069, 2025). "Pedigree analysis identified the same KRT74 variant in the proband’s mother and brother; however, neither exhibited alopecia." (PMID 40766069, 2025). "This case suggests that KRT74 variants may contribute to immune dysregulation in alopecia areata, highlighting the potential role of JAK inhibitors in genetically predisposed alopecia cases." (PMID 40766069, 2025).
alopecia areata (1 paper, 2025). Loss of scalp and body hair involving microscopically inflammatory patchy areas. "The exact mechanism by which KRT74 variants contribute to alopecia areata pathogenesis remains to be elucidated." (PMID 40766069, 2025). "In conclusion, our findings suggest that KRT74 variants may play a role in the development of alopecia areata, highlighting the need for further studies to investigate this association." (PMID 40766069, 2025). "Further research is warranted to explore this potential connection and to determine whether KRT74 variants could serve as biomarkers for alopecia areata susceptibility or targets for therapeutic intervention." (PMID 40766069, 2025). "Larger cohorts with longitudinal data are needed to clarify whether KRT74 variants represent a risk modifier in polygenic alopecia areata." (PMID 40766069, 2025).
alopecia totalis (1 paper, 2025). Alopecia totalis is a form of alopecia areata, an inflammatory disease of the hair follicle, characterized by a complete loss of hair of the entire scalp which becomes glabrous. "We report the case of an 8-year-old boy with alopecia totalis harboring a heterozygous KRT74 variant." (PMID 40766069, 2025). "We present a case of an 8-year-old boy with a heterozygous KRT74 variant who developed alopecia totalis." (PMID 40766069, 2025). "In our case study, we identified a heterozygous variant in KRT74 in an 8-years-old patient presenting with alopecia totalis, an immune-mediated disorder." (PMID 40766069, 2025).
hair disorder (1 paper, 2020). "We used our highest resolution keratin 1B structure as a template for homology-modeling the 1B heterotetramers of keratin 5/14 (associated with blistering skin disorders), keratin 8/18 (associated with liver disease), and keratin 74/28 (associated with hair disorder)." (PMID 32927888, 2020).
KRT74 also shares sentences with these, for which no sentence is quoted: Ectodermal Dysplasia (2 papers); amyloidosis (1); anonychia congenita (1); autosomal dominant woolly hair (1); ectodermal dysplasia hair and nail type 4 (1); liver disease (1); monilethrix (1).